BCL2 (BCL2 apoptosis regulator)
Diseases named in the same sentence as BCL2 in open-access papers (continued):
Sharing a sentence is not in itself a finding about the gene and the disease.
tumor (continued). "Statins promote apoptosis by upregulating pro-apoptotic proteins while downregulating anti-apoptotic ones (bcl-2), and also impair the metastatic potential of tumor cells by inhibiting cell migration, attachment to the extracellular matrix and invasion of the basement membrane." (PMID 34362212, 2021). "Compared with apatinib treatment alone, the combination of CQ and apatinib significantly increased the expression of Bax and inhibited the expression levels of Bcl2, pAKT and pmTOR, which suggested that the inhibition of autophagy enhanced the effect of apatinib on tumor cell apoptosis." (PMID 34229754, 2021). "The apoptotic process of tumor cells could be activated by decreasing in Bcl-2 and increasing in Bax." (PMID 34945511, 2021). "Indeed, studies in humans demonstrated that lapatinib is useful in patients with triple-negative breast tumors, by activating NF-kB and the anti-apoptotic Bcl-2 protein, sensitizing tumor cells to the annexin A6 upregulation and inducing apoptosis." (PMID 33800900, 2021). "B cell lymphoma-2 (BCL-2) homology domain 3 (BH3) mimetics are antagonists that can bind with the hydrophobic Bcl-2 homology (BH) groove of Bcl-2 family proteins, thereby inhibiting these pro-survival proteins and restoring the apoptotic processes in tumor cells." (PMID 34298601, 2021). "Downregulation of the death suppressor Bcl-2 and activation of caspase-8 and bax might be inhibiting tumour growth and progression through promoting apoptosis." (PMID 34181325, 2021). "Furthermore, this compound activates the expression of pro-apoptotic proteins, including Bak and Bax, and inhibits the expression of anti-apoptosis proteins, including Bcl-xL and Bcl-2 resulting in apoptotic induction in tumor cells." (PMID 34319031, 2021). "Bcl-2 and Bax levels are closely related to the apoptosis in tumor cells." (PMID 33385064, 2021). "In animal models, the combined treatment of ZD55-SATB1+DTX and endocrine therapy effectively inhibited the growth of xenograft tumor, accompanied by increased expression of caspase-3 and caspase-8, and decrease expression of Bcl-2 and angiogenesis marker CD31 compared to other treatment groups." (PMID 33613773, 2021). "Therefore, exogenous dysregulation of miR-188-5p in the MM cells triggered both cyclin/Rb/E2F-related signaling and Bcl-2/Bax/caspase-related pathway to modulate cell fate during tumor development." (PMID 33944676, 2021). "BC cell-derived IL-1α also induces expression of TSLP from tumor infiltrating myeloid cells, and TSLP, in turn, induces expression of B cell lymphoma-2 (Bcl-2) in tumor cells, promotes tumor cell survival, and skews the TME toward Th2 inflammation, sustaining lung metastatic survival." (PMID 34602858, 2021). "Notably, EBV DNA positivity was positively correlated with BCL-2 expression, an anti-apoptotic protein in tumor cells." (PMID 33917480, 2021). "As a result, we were able to identify mutations that correlated significantly with tumor cell sensitivity to PRC2 knockout, including SWI/SNF, COMPASS/COMPASS-like subunits and BCL2, warranting the investigation of these genes as potential markers of sensitivity to PRC2-targeting drugs." (PMID 34202528, 2021). "In addition, Bcl-2 overexpression is related to changes in the apoptosis pathway and in the subsequent progression of the tumor." (PMID 33718274, 2021). "Of note, Bcl2 mRNA expression in PCa biopsies correlated with extracapsular extension of the tumor." (PMID 33805590, 2021).
tumor (continued). "Bcl-2 and Bax are the major proteins of the Bcl-2 family with roles in tumor progression." (PMID 33995644, 2021). "In our case, the tumour cells are positive for BCL-2, CD34 and STAT6." (PMID 34849218, 2021). "In addition, ESCC with high expression of Bcl-2 was correlated with deeper tumor invasion, more advanced stages, and lymph node metastasis." (PMID 34257544, 2021). "Additionally, inherent resistance to Bcl-2 inhibition by venetoclax has been previously reported in tumor-derived human B cell lines." (PMID 34381700, 2021). "To confirm whether miR‐140‐3p overexpression regulates the expression of BCL9 and BCL2, we performed real‐time PCR on xenograft tumor tissues." (PMID 33838016, 2021). "The results of this research and others, which show that Bcl-2 family members have cell cycle inhibitory functions, now provide an explanation for how Bcl-2 downregulation and of Bax upregulation may play a role in tumor progression." (PMID 34698080, 2021). "Preliminary studies on the anti-tumour mechanism of BAP 16 disclosed that it could induce dose-dependent cell apoptosis of HepG2 cells through down-regulating the expression of Bcl-2 and up-regulating the expression of Bax and C-Caspase-3." (PMID 34284695, 2021). "In addition, formononetin can also regulate Bcl-2, caspase-3, and other signaling pathways, inhibit tumor cell proliferation, and prevent tumor cell invasion." (PMID 34925533, 2021). "Consequently, their anti-tumor efficacy depends upon the expression of their respective targets, the anti-apoptotic BCL2 proteins." (PMID 34576319, 2021). "To determine whether a similar BCL-2 upregulation occurs in lapatinib-treated patients, we evaluated gene expression within tumor biopsies, collected before and after lapatinib or trastuzumab treatment, from the TRIO-B-07 clinical trial (NCT#00769470)." (PMID 33951110, 2021). "More specifically, several studies reported that increased expression of S100A6 promoted cell proliferation by regulating the expression of IL‐8, CDK5, CDK4, MCM7, Bcl2, and could be used as a marker of tumor aggressiveness in gastric cancers." (PMID 34857857, 2021). "ERN, LP-ERN and Tf-LP-ERN enhanced the expression levels of Bax, Bad, and PUMA, promoted the cleaved caspase-3, cleaved-9 and PARP-1, and reduced the expression level of Bcl-2, which induced apoptosis and thus to inhibited tumor growth in xenotransplanted BALB/c nude mice." (PMID 34513705, 2021). "As described, curcumin effectively inhibits Bcl-2 and enhances tumor cells death." (PMID 35010907, 2021). "Meanwhile, miR-143 can activate Caspase-3, a downstream signal of Bcl-2, and is associated with increased expression of pro-apoptotic genes PARP, Bcl-2-associated X protein (Bax), Bcl-2 antagonist killer (Bak), and Bcl-2 cell death agonist (Bad), all of which induce apoptosis in tumor cells." (PMID 35116035, 2021). "Clinically, BCL2 expression is associated with favorable clinicopathologic features such as small tumor size, negative node, and low histologic grade." (PMID 34099764, 2021). "Finally, we confirmed that ICT1 protein levels in xenografted tumor tissues had a positive correlation with the expression levels of BCL-2." (PMID 33585660, 2021). "In addition, we used RT-qPCR (right) and Western blot to analyze the expression level of the apoptosis inhibitor protein Bcl-2 in the tumor tissues of each group of mice." (PMID 34521413, 2021).
tumor (continued). "Moreover, a significant reduction was found in tumor incidence and tumor burden in the promotion phase, altering Bax and Bcl2 expressions and leading to apoptosis." (PMID 34575899, 2021). "Differences in the ratio of anti-apoptotic vs. pro-apoptotic Bcl-2 proteins may disturb the balance, favouring tumour cell survival instead of cell death." (PMID 34829751, 2021). "It suggested that the expressions of B-cell lymphoma-2 (Bcl-2) family molecules play important roles in balancing the apoptosis and survive of tumor cells and the family was divided into two main group including apoptotic molecules, such as Bax, and anti-apoptotic molecules such as Bcl-2 and Bcl-XL." (PMID 34715776, 2021). "This process of BHRF1+/SNHG8 high/miR-512-5p low/TRIM28high in EBVaGC directly enhances the activation of a set of tumor-promoting factors, such as proliferation-related genes (BCL-2, CCND1, PCNA, PARP1) and metastasis-related genes (Snail, VIM, CDH1, and CDH2)." (PMID 34722282, 2021). "Worth mentioning, that the tumor tissue of our patient was revealed to hyperexpression of BCL-2." (PMID 33933047, 2021). "Moreover, the expression of STAT3 downstream genes, including c-Myc, Bcl-2 and Bcl-xL in tumor tissue were also downregulated by W2014-S." (PMID 33391507, 2021). "In order to analyze the molecular mechanism by which miR-496 promotes tumor cell apoptosis, western blot was used to detect the expression of critical apoptotic factors in each group, including Bax, Active Caspase 3, Total Caspase 3, and Bcl-2." (PMID 34514167, 2021). "Similarly, Bcl-xL can also drive tumor progression in the presence of Bcl-2 protein-directed therapeutic resistance, while Mcl-1 amplification has been reported in lung and breast cancers and, thus, carries equal levels of importance." (PMID 33925117, 2021). "The proteins of apoptosis markers Bcl-2 and Bax were also assessed in subcutaneous xenograft tumor, the expression of Bcl-2 was showed to significantly increase in sh-ACTA2-AS1 group in comparison with the sh-NC group, while decreased in OE ACTA2-AS1 group in comparison with the vector group." (PMID 33845844, 2021). "Bcl-2 is particularly important proteins that promotes tumor cell survival." (PMID 34976809, 2021). "To determine whether BCL-2 upregulation correlated with the inhibition of tumor proliferation, we performed Ki67 IHC." (PMID 33951110, 2021). "Further investigation will help to better predict tumour sensitivity to Bcl2-inhibitors." (PMID 33494434, 2021). "On immunohistochemistry, the tumor cells had typically strong and diffuse positivity for vimentin and BCL2, focal positivity for CD34, and weak diffuse positivity for CD99 but negativity for cytokeratins AE1–AE3, actin HHF35, actin 1A4, calponin, caldesmon, desmin, S-100 protein, and collagen IV." (PMID 34211794, 2021). "The gray value showed that the mitochondria could significantly decrease the BCL2 level, suggesting that the anti-apoptotic ability of tumor cells might be inhibited." (PMID 34131403, 2021). "Inhibitors of antiapoptotic mechanisms such as BCL2 (B-cell lymphoma 2) inhibitors are being tested in combination with other targeted therapies that modify tumor microenvironment and tumor mitochondrial energy metabolism in hematologic malignancies (detailed in)." (PMID 34461089, 2021).
tumor (continued). "It is related to tumor progression, metastasis, drug resistance, and promotes apoptosis at mitochondria by activating proteins Bax and Bak and by inhibiting the anti-apoptotic proteins Bcl-XL, Bcl-2, and Mcl-1." (PMID 34955827, 2021). "The reduced BCL-2 gene expression in FaDu tumor cells could explain the high percentage of apoptosis recorded by RSV alone or RSV + CisPt-treated cells." (PMID 34204834, 2021). "Nonetheless, we would predict that tumor populations distinguished by elevated BCL-2 could contribute to residual and recurrent disease." (PMID 33951110, 2021). "Indeed, overexpression of GAS5 promoted apoptosis by decreasing the expression of the anti-apoptosis protein BCL-2 and inhibited tumor resistance to therapy in bladder and cervical cancers." (PMID 33483590, 2021). "Increased Bax/Bcl-2 ratio up-regulates caspase-3, which leads to apoptosis of tumor cells." (PMID 34364387, 2021). "Morphologically, BCL2/Sestrin1-deficient tumors resembled FL with a follicular architecture, they displayed markers of a GC phenotype (PNA and BCL6), showed evidence of somatic hypermutation, an increased tumor proliferation based on Ki67 staining." (PMID 34335584, 2021). "Furthermore, miR‐140‐3p expression level and BCL9 or BCL2 mRNA level in tumor tissues were negatively correlated." (PMID 33838016, 2021). "However, high expression of Bcl-2 was associated with more advanced ESCC stages, deeper tumor invasion, and lymph node metastasis." (PMID 34257544, 2021). "Moreover, we further disclosed the underlying of collagen/ITGB1 induced tumor progression, which was dependent on a BCL9L/β-catenin/BCL2 signaling pathway." (PMID 34319913, 2021). "Recently, the development of new BCL2 inhibitors for clinical application, combined with various anticancer drugs to enhance the therapeutic effects, has become a research highlight in the field of anti-tumor drugs." (PMID 34259934, 2021). "Furthermore, by comparing the level of expression of the BCL-2 gene in the two tumor lines, PE/CA-PJ49 and FaDu (p < 0.03, *), the different action mode of RSV was observed." (PMID 34204834, 2021). "In short, we showed a concrete example of how to circumvent the intrinsic tumor resistance to a copper complex in this study; by extension, silencing the Bcl-2 gene provides a general scheme for getting rid of the Bcl-2-related tumor resistance to metal-based anticancer drugs." (PMID 34163720, 2021). "Additionally, we performed immunohistochemical staining for SOX10, CD3, CD4, CD8, BCL2, and caspase-3 in lgCMN tissues to detect the tumor-infiltrating lymphocytes (TILs) and antiapoptotic phenomenon." (PMID 34912899, 2021). "The c-MYC gene could cooperate with other oncogenes such as BCL-2, and thus it might influence the mechanisms involved in tumor surveillance." (PMID 34204834, 2021). "In addition, among all treatment groups, the FYD + IL-12 + BMSC group showed the highest serum IL-12 and IFN-γ levels and Bax and Bcl-2 expressions in tumor cells (P < 0.05)." (PMID 33827606, 2021). "In addition, Rh favourably inhibited tumours by activating the secretion of apoptosis-related proteins, such as caspase-3, BCL-2 and BAX, in tumour cells after treatment." (PMID 33632266, 2021). "The expression of bcl-2 rises with increasing grade of tumor." (PMID 34178320, 2021). "All anti-apoptotic Bcl-2 proteins seem to play the role of oncoproteins, and pro-apoptotic proteins may have a role as tumor suppressors." (PMID 34638779, 2021). "Besides, researchers suggested that the tumor cells harboring ARID1A alterations showed the therapeutic sensitivity to Bcl-2 inhibitors which indicated the activation of apoptotic pathways induced by ARID1A alterations or expression loss." (PMID 34715776, 2021). "In addition, BCL9 and BCL2 protein levels were increased in tumor tissues compared with adjacent normal tissues." (PMID 33838016, 2021).
tumor (continued). "The association of the apoptosis-related factors Bcl-2 and Bax with BC tumorigenesis has been clarified; patients who are negative for distant metastasis with a lower degree of tumor differentiation exhibit lower Bcl-2 expression and higher Bax expression." (PMID 33420414, 2021). "The high expression of BCL2 is closely related to tumorigenesis, and the overexpression of BCL2 family proteins promotes the occurrence and development of tumors, while its inhibition is related to anti-tumor characteristics." (PMID 33747905, 2021). "Additionally, western blot data showed that gracillin induced the cleavage of PARP and expression of TIPE2, and inhibited the phosphorylation of AKT and expression of bcl-2 in the tumor tissue of mice." (PMID 34630074, 2021). "Patients whose tumor demonstrate bcl-2 positivity even with locoregionally advanced disease, appear to have a high likelihood of cure with aggressive combined modality therapy and may be treated successfully with less toxic therapy." (PMID 34178320, 2021). "Moreover, C6M1:siRNA reduced tumor growth through the silencing of the anti-apoptotic protein Bcl-2 after an intratumoral injection in mice." (PMID 34065544, 2021). "CDK9 is also responsible for transcription of anti-apoptotic factors, that belong to Bcl-2 superfamily: Mcl-1 (Myeloid cell leukaemia-1), Bcl-2 (B-cell CLL/Lymphoma 2), and XIAP (X-linked inhibitor of apoptosis), making CDK9 potential source of inhibition for anti-tumor purposes." (PMID 33805800, 2021). "For instance, this activation of stress induced MAPK could exert its tumor suppressive role through increased production of proapoptotic proteins, Bax and Bim, and decreased production of anti-apoptotic proteins, Bcl2, hence promoting apoptosis." (PMID 33430381, 2021). "Consequently, low levels of Keap1 induced by epigenetic promoter silencing should enhance apoptosis escape and survival of BC tumor cells via both Nrf2 and Bcl-2." (PMID 34316328, 2021). "Given the favorable safety profile of venetoclax, a greater understanding of the mechanisms of primary as well as acquired resistance to this agent is needed to improve or extent venetoclax-based therapies, and potentially other Bcl-2 inhibitors, to various tumor types including solid tumors." (PMID 33799470, 2021). "Under chemotherapy selective pressure, tumor cells can become “addicted” to Bcl-2 expression for survival, so an obvious strategy to overcome this resistance mechanism may be the use of Bcl-2 inhibitors." (PMID 33525637, 2021). "Here, we found some candidate miRNAs that target Bcl-2 by sequence matching in bioinformatics analyses, and we detected a major decrease specifically in miR-383 in specimens of GC among other miRNAs, comparing with the paired non-tumor tissue." (PMID 33402109, 2021). "Another potential survival pathway regulated by HIF1α in tumor cells is through the increased expression of BCL2/adenovirus E1B 19 kDa protein-interacting protein 3 (BNIP3), a component of autophagosomes that complexes with p62 LC3 complex proteins to initiate a survival mechanism of self-renewal." (PMID 34396954, 2021). "Overexpression of Bcl-2 is often considered as a protective effect of various apoptotic stimuli, while down-regulation of Bcl-2 may induce apoptosis of tumor cells." (PMID 34819867, 2021). "Recent studies have also associated phosphoinositide 3-kinases with protein kinase B (PI3K/AKT) signaling pathway activation with upregulation of Bcl-2 and caspase-3, together with the downregulation of Bax and cleaved-caspase-3 with decreased tumor cell sensitivity towards 5-FU cytotoxicity." (PMID 34571731, 2021).